HSD11B1 (hydroxysteroid 11-beta dehydrogenase 1)
Diseases named in the same sentence as HSD11B1 in open-access papers (continued):
Sharing a sentence is not in itself a finding about the gene and the disease.
tumor (17 papers, 2015 to 2026). "Our data suggest, however, that Tregs are a major effector of intratumor glucocorticoid-mediated immunosuppression because loss of Treg GR signaling contributed to a reduction in tumor growth similar to that seen with the loss of tumor Hsd11b1." (PMID 37471141, 2023). "Herein, increased HSD11B1 expression was interconnected with poor survival of ccRCC patients, supporting a potential association between HSD11B1 expression and tumor progression and clinical outcome." (PMID 34845968, 2021). "The CNG and increased protein expression of HSD11B1 were strongly associated with the presence of epithelioid histology, increased tumor size, mitosis, and risk level defined by NIH and NCCN schemes (p ≤ 0.002 for all the associations)." (PMID 30388854, 2018). "At the genetic and protein levels, HSD11B1 CNG and elevated HSD11B1 expression highly characterized the GISTs that exhibit epithelioid histology, increased tumor size and mitosis, and high-risk levels." (PMID 30388854, 2018). "In addition, we performed association analysis between HSD11B1 and immune cells to evaluate its correlation with tumor microenvironment." (PMID 34845968, 2021). "Co-staining of HSD11B1 with CD68+ cells confirmed that HSD11B1 was expressed in tumor-infiltrating macrophages." (PMID 38170044, 2024). "The combination of the HSD11B1 inhibitor with anti-PD-1 was then tested in mice bearing orthotopic Renca tumors and tumor growth was assessed by MRI and PET scans." (PMID 38170044, 2024). "Mechanistically, we demonstrated that HSD11B1 inhibition combined with resiquimod increased T cell-mediated cytotoxicity to tumor cells by stimulating the antigen-presenting capacity of dendritic cells." (PMID 38170044, 2024). "HSD11B1 was mainly expressed in tumor-infiltrating immune myeloid cells as seen by immunohistochemistry in RCC patient samples." (PMID 38170044, 2024). "In an intrarenal mouse tumor model, HSD11B1 inhibition increased the survival of mice treated with anti-PD-1." (PMID 38170044, 2024). "A positive staining of HSD11B1 was mainly detected in infiltrating cells with 11/20 patients showing more than 1% of HSD11B1-positive cells, that were mainly found in the core of the tumor." (PMID 38170044, 2024). "In contrast, corticosterone concentrations were approximately 3-fold higher in tumors than in the spleen, an increase that was due to tumor-generated corticosterone because B16 Hsd11b1–/– tumors had levels similar to those in the spleen." (PMID 37471141, 2023). "Tumor-derived corticosterone was demonstrated to act locally, as wild-type and Hsd11b1-knockout B16 tumors that were injected in the contralateral flanks of the same animal exhibited differences in in vivo growth." (PMID 37712416, 2023). "In this study, we found that tumor cell–intrinsic expression of Hsd11b1 allows generation of immunoregulatory glucocorticoids that act upon immune cells, especially Tregs, to suppress local antitumor immunity and promote tumor growth." (PMID 37471141, 2023). "Extra vigilance is recommended if 11β-HSD1 use is indicated in patients with such HSD11B1-expressing tumours." (PMID 36940215, 2023). "These patterns are consistent with the findings in mice and with a role for tumor HSD11B1 in suppressing immunity and promoting growth of a variety of human cancers." (PMID 37471141, 2023). "Corticosterone levels were similar in the spleens of control and Hsd11b1–/– B16 tumor-bearing animals." (PMID 37471141, 2023). "The finding that tumor Hsd11b1 expression upregulated markers of Treg activity prompted us to specifically investigate the role of Treg glucocorticoid signaling in tumor growth." (PMID 37471141, 2023). "Across tumor types, HSD11B1 expression correlated positively with expression of the glucocorticoid-responsive genes TSD22D3 (GILZ), DUSP1, and FKBP5." (PMID 37471141, 2023). "Wilcoxon rank-sum test showed that HSD11B1 expression in tumor group was significantly higher than that in normal group." (PMID 34845968, 2021).
tumor (continued). "Thus, tumor Hsd11b1 expression is sufficient to substantially increase intratumor corticosterone levels." (PMID 37471141, 2023). "Because Hsd11b1 expression is widespread in healthy mammalian tissues and upregulated in multiple human cancer types, its actions in driving tumor growth may be similarly widespread." (PMID 37471141, 2023). "To determine whether the growth-promoting effect of Hsd11b1 was due to direct alterations in tumor cell–intrinsic proliferation, we compared cell growth in vitro." (PMID 37471141, 2023). "Furthermore, when we used gene signatures to estimate the frequency of tumor-infiltrating cells across tumor types, HSD11B1 expression was negatively correlated with infiltrating Tconv frequency and positively correlated with infiltrating Treg frequency." (PMID 37471141, 2023). "Because genetic disruption of tumor-expressed Hsd11b1 suppressed tumor growth in vivo, we asked whether administration of 11β-HSD1 inhibitors would have the same effect." (PMID 37471141, 2023). "The importance of Tregs as a target of tumor glucocorticoids is underscored by the minor effect of tumor Hsd11b1 deficiency in the absence of Treg GR." (PMID 37471141, 2023). "Here, we find that multiple tumor types express Hsd11b1 and produce active glucocorticoids." (PMID 37471141, 2023). "The results suggested that HSD11B1 was highly significantly associated with lower risk of recurrence in HGSOC, and response to platinum-based therapy was related to distinct gene-expression patterns of tumor immune-system." (PMID 34604063, 2021). "Thirdly, our correlation analysis showed the significant prevalence of HSD11B1 mutations in GISTs that belonged to high-risk category; HSD11B1 mutations were also marginally and significantly associated with short DFS in high-risk GISTs and GISTs with tumor relapses, respectively." (PMID 30388854, 2018). "Among all the 58 GISTs sequenced, 20 cases developed tumor relapse, including 5 and 15 cases with and without HSD11B1 mutations, respectively." (PMID 30388854, 2018). "Importantly, B16 control and Hsd11b1–/– tumors grew identically in Cyp11b1Actin–Cre mice, demonstrating that metabolites of adrenal-derived glucocorticoids are necessary for tumor-specific regeneration and promotion of tumor growth." (PMID 37471141, 2023). "Hsd11b1 deficiency did not affect cell growth in vitro, but substantially delayed tumor growth in vivo in wild-type, immunocompetent mice independently from the expression of GR by tumor cells themselves." (PMID 37712416, 2023). "Interestingly, while high CYP11A1 and HSD11B1 expression resulted in poor survival, suggesting that tumours efficiently suppressing the immune system via glucocorticoids have a growth advantage, high NR0B2 was beneficial for survival, likely due to increased suppression of LRH‐1." (PMID 36861295, 2023). "In flow cytometric analysis, stable HSD11B1 silencing in both GIST cell lines significantly increased the percentage of tumor cells in the G2/M phase, implying that HSD11B1 might exert its pro-proliferative effect partially by promoting progression through the G2/M checkpoint." (PMID 30388854, 2018). "First, cortisol-d4 was administered to non-tumor-bearing mice treated with ABT-384 and HSD11B1 activity was quantified." (PMID 38170044, 2024). "Using peripheral blood mononuclear cells from healthy donors or immune cells isolated from the tumor of RCC patients, we showed that the pharmacological inhibition of HSD11B1 improved the response to the immune checkpoint inhibitor anti-PD-1." (PMID 38170044, 2024). "Tumor cell Hsd11b1 expression markedly increased intratumor corticosterone levels, reduced CD8+ TIL activity, and increased the immunosuppressive function of tumor-infiltrating Tregs." (PMID 37471141, 2023). "Although deletion of Hsd11b1 in MC38 cells prevented in vitro corticosterone generation, it had only a modest effect on in vivo tumor growth." (PMID 37471141, 2023).
tumor (continued). "It appears that the enzymes ChEH, HSD11B1 and HSD11B2 and CYP27A1 sit at a fulcrum balancing the formation from 5α,6-EC of the tumour suppressor DDA and from 5,6-EC, through 3β,5α,6β-triol, the oncometabolite 3β,5α-diHC-6O or the bile acid 3β,5α,6β-triHBA." (PMID 31009661, 2019). "Carbenoxolone and PF-915275 inhibited B16 tumor growth to a degree similar to that seen with B16 tumors lacking Hsd11b1 expression." (PMID 37471141, 2023). "If tumor-derived corticosterone acts locally in a paracrine manner, rather than systemically, we would expect Hsd11b1–/– tumors to grow more slowly than controls even when implanted in the same animal." (PMID 37471141, 2023). "Thus, although HSD11B1 inhibition did not confer higher antitumoral efficacy to anti-PD-1 treatment, the combination impacted the tumor immune phenotype." (PMID 38170044, 2024).
cancer (12 papers, 2008 to 2026). A tumor composed of atypical neoplastic, often pleomorphic cells that invade other tissues. "We propose that HSD11B1 contributes to cancer-associated immunosuppression by regulating the activation of myeloid cells and their capacity to induce an effective T cell response." (PMID 38170044, 2024). "In contrast, Hsd11b1 was expressed by cancer-associated fibroblasts, T cells, MAIT cells, and a small proportion of macrophage/monocytes/neutrophils." (PMID 37471141, 2023). "Proliferative phenotypes induced by high expression of HSD11B1 are associated with poor cancer prognosis." (PMID 34845968, 2021). "In vivo drug screen using this model identified adrenosterone, an inhibitor for hydroxysteroid (11-beta) dehydrogenase 1 (HSD11β1), as having a potential to suppress metastatic dissemination of cancer cells." (PMID 37251091, 2023). "However, according to the provisional data catalogued in the cBioPortal platform for cancer genomics, HSD11B1 amplification might occur in varying but significant proportions of common cancers, such as prostate (13.6–26.2%), breast (9.5–17.6%), and renal cell (9.1%) carcinomas." (PMID 30388854, 2018). "Because Hsd11b1 is widely expressed in both mouse and human tissues, 11β-HSD1 may be a therapeutic target in many cancers." (PMID 37471141, 2023). "In humans, HSD11B1 was expressed in many cancer types, but CYP11B1 and CYP11B2 had low or absent expression." (PMID 37909339, 2023). "Given that HSD11B1 expression is upregulated in many human tumors and that inhibition of 11β-HSD1 is well tolerated in clinical studies, these data suggest that targeting 11β-HSD1 may be a beneficial adjunct in cancer therapy." (PMID 37471141, 2023).
metabolic disease (4 papers, 2017 to 2024). A congenital disorder (due to inherited enzyme abnormality) or acquired (due to failure of a metabolically important organ) disorder resulting from an abnormal metabolic process. "Since HSD11B1 has been associated with several metabolic disorders, it has been investigated as a novel target for potential therapeutic drugs." (PMID 29206210, 2017). "Castration further leads to glycolipid metabolic disorders and increased expression of inflammatory cytokines by affecting the expression of HSD11B1, SGK1, PCK1, and SLC2A4 in abdominal adipose tissues and their regulatory factors." (PMID 35456474, 2022). "In this study, we established immortalized porcine HSD11B1-TG (SV11βTG) hepatocytes, which are useful for investigation of metabolic disorders, through transduction of SV40LT antigen." (PMID 29206210, 2017). "HSD11B1 is closely related to the accumulation and metabolic disorders of abdominal fat." (PMID 35456474, 2022). "The immortalized HSD11B1-TG hepatocytes may be useful for studying traits and potential therapeutic drugs for treatment of metabolic disorders induced by overexpression of HSD11B1." (PMID 29206210, 2017).
psychiatric disorder (1 paper, 2019). A disorder characterized by behavioral and/or psychological abnormalities, often accompanied by physical symptoms. "We then examined methylation in a shortlist of genes that were previously associated with early life stress and psychiatric disorders as well as placental functioning: Ank3, Avp, Avpr1a, Avpr1b, Bdnf, Cacna1c, Cyp11b1, Cyp11b2, Fkbp5, Hsd11b1, Igf2, Morc1, Nr3c1, Oxt, Oxtr, Pclo, Slc6a4." (PMID 30655507, 2019).
HSD11B1 also shares sentences with these, for which no sentence is quoted: hyperandrogenism (4 papers); clear cell renal cell carcinoma (3); Cushing syndrome (2); endometrial cancer (2); insulin-resistant diabetes (2); acute myelogenous leukemia (1); adenocarcinoma (1); Alzheimer disease (1); benign hereditary chorea (1); Brain atrophy (1); brain tumors (1); cognitive decline (1); dyslipidaemia (1); Dystonia (1); eczema (1); endothelial dysfunction (1); epidermolysis bullosa (1); Hyperinsulinemia (1); hypertriglyceridemia (1); inflammatory bowel disease (1); intrauterine growth restriction (1); lung carcinoma (1); lymphoma (1); magnesium deficiency (1); measles (1); Miscarriage (1); non-Hodgkin lymphoma (1); non-small cell lung carcinoma (1); osteosarcoma (1); renal cell carcinoma (1).
A further 6 diseases each share a sentence with HSD11B1 in 1 paper.